PCNA (proliferating cell nuclear antigen)
Diseases named in the same sentence as PCNA in open-access papers (continued):
Sharing a sentence is not in itself a finding about the gene and the disease.
endothelial dysfunction (2 papers, 2024 to 2025). In vascular diseases, endothelial dysfunction is a systemic pathological state of the endothelium (the inner lining of blood vessels) and can be broadly defined as an imbalance between vasodilating and vasoconstricting substances produced by (or acting on) the endothelium. "Immunofluorescence staining revealed significant endothelial dysfunction and senescence in the HHcy-exposed rats, particularly in the Mid-old+HHcy group, as shown by decreased Laminb1, PCNA and increased p21, IL-6 expression." (PMID 41281764, 2025).
Ewing sarcoma (2 papers, 2014 to 2017). A small round cell tumor that lacks morphologic, immunohistochemical, and electron microscopic evidence of neuroectodermal differentiation. "Combination of EWS shRNA plasmid transfection and TFL treatment drastically down regulated hTERT and PCNA indicating that inhibition of cell proliferation promoted differentiation of Ewing’s sarcoma cells." (PMID 27547487, 2014).
fibrosis (2 papers, 2021 to 2024). the formation of excess fibrous connective tissue in an organ or tissue in a reparative or reactive process. "In the current study, PCNA expression was observed to be increased in the fibrosis group treated with resveratrol, compared to the fibrosis group." (PMID 39055873, 2024). "As well, PCNA downregulation was observed in the liver with steatohepatitis and fibrosis in HCV-infected patients." (PMID 34638467, 2021).
gallbladder carcinoma (2 papers, 2013 to 2020). "We found that ATP was used up after DU145 cells treated with NCTD, which revealed a possible mechanism involved in the down regulation of the proliferation-relate genes PCNA, Ki-67 and p27 in gallbladder carcinoma cells." (PMID 24367681, 2013). "In gallbladder cancer, it was reported that NCTD inhibited the expression of GBC-SD cell proliferation-related gene proteins PCNA (proliferating cell nuclear antigen) and Ki-67, this may be one of the mechanisms by which NCTD inhibit the proliferation and growth of tumor cells." (PMID 32514288, 2020).
gastritis (2 papers, 2021 to 2022). Inflammation of the stomach. "The PCNA expression was substantially higher in cases of gastritis and helicobacter pylori infection." (PMID 36080365, 2022). "Interestingly, the positive index of E2F nuclear staining was higher in H. pylori-infected gastric mucosa than in non-infected gastritis samples, and E2F1 was co-localized with proliferating cell nuclear antigen (PCNA)." (PMID 34136392, 2021).
glomerulosclerosis (2 papers, 2022 to 2025). A hardening of the kidney glomerulus caused by scarring of the blood vessels. "Similar results were obtained by Western blotting analyses of multiple mesangial cell activation and glomerulosclerosis-related proteins including FN, collagen IV, α-SMA, c-Myc, and PCNA." (PMID 40303345, 2025).
hemangioma (2 papers, 2013 to 2021). A benign vascular lesion characterized by the formation of capillary-sized or cavernous vascular channels. "In contrast, proliferating cell nuclear antigen (PCNA) was mainly expressed in proliferating hemangiomas." (PMID 33400686, 2021). "Similar to PCNA, NGBR was mainly expressed in proliferating hemangiomas (right)." (PMID 33400686, 2021).
HIV encephalitis (2 papers, 2016 to 2023). "Fischer‐Smith T found an accumulation of PVMs in HIV encephalitis and the role of CD16+/PCNA+ in mononuclear phagocyte trafficking." (PMID 36514189, 2023).
Huntington disease (2 papers, 2021 to 2025). Huntington disease (HD) is a rare neurodegenerative disorder of the central nervous system characterized by unwanted choreatic movements, behavioral and psychiatric disturbances and dementia. "For example, in the human brain tissues of patients who died with Huntington’s disease, a significant increase in the levels of proliferating cell nuclear antigen (PCNA), beta III-tubulin (a neuronal marker), and glial fibrillary acidic protein (GFAP- a glial cell marker) can be found." (PMID 34070012, 2021).
intestinal polyp (2 papers, 2012 to 2022). Discrete abnormal tissue masses that protrude into the lumen of the intestine. "To assess whether Riccardin D efficacy is associated with its anti-proliferative and pro-apoptotic effects, we examined the expressions of PCNA, TUNEL and apoptotic proteins in intestinal polyps." (PMID 22432006, 2012).
intestinal tumor (2 papers, 2013 to 2021). "PCNA and HIF1α expression increased three-fold in intestinal tumors (P < 0.01) compared to normal mucosa." (PMID 23718763, 2013). "Immunochemical data showed an increase in active caspase-3, PCNA expression, and downstream signaling of phosphorylated AKT in kras+/LPS zebrafish compared with kras+ zebrafish, which suggests that LPS is associated with intestinal tumor formation." (PMID 34440178, 2021).
invasive carcinoma (2 papers, 2007 to 2008). A carcinoma that is not confined to the epithelium, and has spread to the surrounding stroma. "However PCNA was expressed more progressively from a lower grade to the higher degrade and invasive carcinomas." (PMID 18786253, 2008). "Our results showed that the presence of PCNA does not clearly distinguish between nonproliferative BBD lesions and proliferative BBD lesions (with or without atypia), or between in situ carcinomas and invasive carcinomas." (PMID 17164758, 2007).
inverted papilloma (2 papers, 2014 to 2015). An endophytic benign papillary epithelial neoplasm that results from the invagination and proliferation of epithelial cells in the underlying stroma. "In that study, the PCNA expression rates in two cases of malignant inverted papilloma were higher than in benign IUPs." (PMID 26208279, 2015).
jaw cysts (2 papers, 2021 to 2022). "Previous studies have shown that OKCs consistently express higher PCNA and Ki-67 than other jaw cysts, indicating its inherently increased proliferative potential." (PMID 34261507, 2021).
Kaposi's sarcoma (2 papers, 2015 to 2022). A malignant neoplasm characterized by a vascular proliferation which usually contains blunt endothelial cells. "Previously, iron depletion was reported to induce cell cycle arrest by reducing cyclin D1 levels in mantle cell lymphoma cells and by reducing PCNA and cyclin D1 levels in a dose-dependent manner in immortalized Kaposi’s sarcoma cells." (PMID 35631174, 2022).
kidney damage (2 papers, 2019 to 2025). "Interestingly, resistance exercise modulated markers of kidney damage, reducing macrophage infiltration in kidney tissue, lowering the number of PCNA-positive cells, and decreasing the incidence of glomerular tubularization in all studied groups." (PMID 40491452, 2025). "Moreover, in mice with adriamycin-induced nephropathy, some podocytes began to express PCNA, which implied that some podocytes entered the cell cycle and proliferated." (PMID 31801948, 2019). "In our animal model, resistance training reduced markers of kidney damage in rats undergoing testosterone-based cross-hormone therapy (CHT), including decreased macrophage infiltration, reduced cell proliferation (fewer PCNA-positive cells), and less glomerular tubularization." (PMID 40491452, 2025).
Kidney tumors (2 papers, 2009 to 2015). "Kidney tumors in mice treated with either drug showed robust growth with development of relatively large papillary and solid tumors, and re-expression of PCNA." (PMID 19527517, 2009). "Human kidney tumor is stained for CD31 (mouse antibody) in green, Vimentin (guinea pig antibody) in red, E-Cadherin (mouse antibody) in white, and PCNA (mouse antibody) in magenta plus DAPI in blue." (PMID 25826597, 2015).
laryngeal carcinoma (2 papers, 2004 to 2009). Carcinoma that arises from the laryngeal epithelium.
malaria (2 papers, 2003 to 2012). Malaria is a serious and sometimes fatal disease caused by a parasite that commonly infects a certain type of mosquito which feeds on humans. "This functional gene group, with peak expression around 32 hpi, contains the previously characterized P. falciparum DNA Polα, DNA Polδ, and proliferating cell nuclear antigen, as well as the vast majority of the DNA replication components predicted by the malaria genome sequencing consortium." (PMID 12929205, 2003).
malignant glioma (2 papers, 2015 to 2022). A grade III or grade IV glioma arising from the central nervous system. "Among them are KI67 and proliferating cell nuclear antigen (PCNA), commonly accepted proliferation markers associated with course of various cancers, including malignant gliomas." (PMID 25738367, 2015). "However, the DNA binding cavity for PCNA would be occupied by the ncRNAs AC008738.2, AC102941.1, and AL136115.1, hindering and impeding DNA replication and thus suppressing proliferation and other cell cycle processes in malignant glioma." (PMID 35194922, 2022).
malnutrition (2 papers, 2013 to 2022). Inadequate nutrition resulting from poor diet, malabsorption, or abnormal nutrient distribution. "In a state of nutritional deficiency and oxidative stress, ESCC induces continuous growth and resistance to chemotherapy via the ACSS2/AMP-activated protein kinase (AMPK)/proliferating cell nuclear antigen (PCNA) pathways." (PMID 36106333, 2022). "Malnutrition increases apoptosis of immature double positive CD4+CD8+ lymphocytes and decreases thymocyte proliferation as demonstrated in rodents by the reduction of proliferating cell nuclear antigen (PCNA) expression in thymocytes." (PMID 23730302, 2013).
meningioma (2 papers, 2023 to 2024). A generally slow growing tumor attached to the dura mater. "Although only in single studies, KPNA2, CDK6, Cox-2, MCM7 and PCNA are proposed as additional markers with high expression that are related with poor prognosis of meningioma patients." (PMID 38758750, 2024). "This protein is overexpressed in meningiomas, and its expression level correlates with proliferation markers such as Ki67 and PCNA in meningeal tumors." (PMID 37686289, 2023).
metastatic melanoma (2 papers, 2011 to 2013). A melanoma that has spread from its primary site to another anatomic site. "Although some of these genes (e.g. cell cycle genes CCND2, CCNE1 and PCNA) had fold changes that were in a different direction when compared to metastatic melanoma patients, this is likely to be due to the active growth of these cells in culture." (PMID 21615965, 2011). "The mRNA expression of several genes involved in cell cycle control and/or proliferation, including the Cyclins B3, E1, G1 and G2; PCNA and RB1 were also decreased in metastatic melanoma." (PMID 21615965, 2011).
middle ear cholesteatoma (2 papers, 2013 to 2021). "To test our hypotheses, firstly we examined the expressions of phosphorylated EGFR (p-EGFR), phosphorylated Akt (p-Akt), cyclinD1, and proliferating cell nuclear antigen (PCNA) in middle ear cholesteatoma and normal EAC skin specimens." (PMID 24311896, 2013).
mucositis (2 papers, 2013 to 2022). Mucositis is inflammation and damage of the mucous membranes lining the mouth and other parts of the gastrointestinal (GI) tract. "It remained unclear if the lower level of PCNA and cyclin-D1 in CS treated groups is caused by a direct suppression effect or due to the mild mucositis resulting in less expression of the genes relevant to crypts regeneration." (PMID 24367389, 2013). "Intestinal proliferation markers were also employed in some studies to assess the effect of mucositis on epithelial intestinal cells, including proliferating cell nuclear antigen (PCNA) and Ki-67." (PMID 36499758, 2022). "Interestingly, elevations of PCNA and cyclin-D1 were observed in all 5-Fu treated groups, suggesting a healing process from the experimental mucositis." (PMID 24367389, 2013).
oral lichen planus (2 papers, 2008 to 2022). Oral lichen planus is a chronic inflammatory oral condition of unknown aetiology characterized by T-cell-mediated chronic immune response and abnormal epithelial keratinization cycle.
osteoarthritis (2 papers, 2021 to 2023). A noninflammatory degenerative joint disease occurring chiefly in older persons, characterized by degeneration of the articular cartilage, hypertrophy of bone at the margins and changes in the synovial membrane. "Taken together, our findings provide strong evidence for a regulatory role for the circSERPINE2/YBX3/PCNA/p21 axis in MSC senescence and the therapeutic potential of si-circSERPINE2 in alleviating aging-associated syndromes, such as osteoarthritis." (PMID 37831180, 2023). "Primary mouse chondrocytes isolated from mice with destabilized medial meniscus (DMM)-induced osteoarthritis had significantly reduced FNDC5 and LC3 expression and weak immunoreactivity of the proliferating cell nuclear antigen (PCNA)." (PMID 34502045, 2021).
papillary thyroid cancer (2 papers, 2016 to 2022). "In papillary thyroid cancer cell lines, OB3 and leptin reduced the expression of PCNA and MCL1 in BHP18-21, however, only leptin reduced the expression of PCNA and c-Myc in BHP2-7 cells." (PMID 27050378, 2016).
papilloma (2 papers, 2012 to 2013). A benign epithelial neoplasm that projects above the surrounding epithelial surface and consists of villous or arborescent outgrowths of fibrovascular stroma. "PCNA is an E2F-regulated gene product which is induced in papillomas by the presence of E7.16,17 E7, which is a viral oncoprotein, can be produced by HPV, and binds to pRb leading to releasing the E2F transcription factor which can activate PCNA gene." (PMID 24353714, 2013). "As we predicted, data showed the expressions of mRNA (P<0.01), protein, and the amount of PCNA-positive cells in papillomas was significantly higher in JWA+/+ than in JWAΔ2/Δ2 mice (P<0.05)." (PMID 22461904, 2012).
periodontitis (2 papers, 2022 to 2025). An acute or chronic inflammatory process that affects the tissues that surround and support the teeth. "Ligature-induced periodontitis combined with F.n. promoted growth of subcutaneously injected SCC7 cells, as shown by increased expression of proliferation markers Ki-67 and PCNA." (PMID 40924302, 2025).
pleural tumor (2 papers, 2013 to 2022). "Examination of the thorax revealed massive MPE in most and visceral/parietal pleural tumors in all mice, which invaded the lungs, chest wall, and mediastinum and uniformly presented as PCNA+ biphasic MPM with mixed sarcomatoid/epithelioid features." (PMID 34898002, 2022). "Almost half of pleural tumor cells displayed nuclear PCNA immunoreactivity, but caspase-3-positive cells were rare." (PMID 23967166, 2013). "For this, pleural tumor tissue was immune-labeled for PCNA and caspase-3." (PMID 23967166, 2013).
prion disease (2 papers, 2020 to 2021). A transmissible disease that is caused by a protein that is able to induce abnormal folding of normal cellular proteins, leading to characteristic spongiform brain changes, which are associated with neuronal loss without an inflammatory response. "For example, nuclear accumulation of proliferating cell nuclear antigen (PCNA) and phosphorylated histone H2A.X proteins, which are indicative of DNA replication and/or repair in other cell types, have been detected in CNS neurons of mice used to model familial CJD and FFI prion diseases." (PMID 32108870, 2020).
renal cell carcinoma (2 papers, 2021 to 2024). "In renal cell carcinoma, overexpression of ASF1B enhanced cell proliferation through up-regulating PCNA (proliferating cell nuclear antigen)." (PMID 34906203, 2021).
Salmonella Infections (2 papers, 2018 to 2025). Infections with bacteria of the genus SALMONELLA. "Our study demonstrated that enteritis-causing Salmonella infection resulted in diminished ISCs activity, as evidenced by the downregulation of Lgr5, PCNA, KRT20, and Villin expression." (PMID 40059168, 2025).
Sezary syndrome (2 papers, 2023 to 2024). Sezary syndrome (SS) is an aggressive form of cutaneous T-cell lymphoma characterized by a triad of erythroderma, lymphadenopathy and circulating atypical lymphocytes (Sezary cells). "In T-cell lymphomas (Sezary syndrome), PCNA was found to be expressed on cancerous T cells and blockade of PCNA using the antibody-mAb14-enhanced NK-mediated lysis of these cells." (PMID 39205238, 2024).
steatosis (2 papers, 2019 to 2022). Increased lipid within the cytoplasm of cells. "Administering GLP1 also caused a rise in the count of PCNA-positive cells and in levels of cyclin D1 and A when compared to grafts from CD donors without treatment in livers with steatosis." (PMID 31835410, 2019).
Telangiectasia (2 papers, 2014 to 2023). Telangiectasias refer to small dilated blood vessels located near the surface of the skin or mucous membranes, measuring between 0.5 and 1 millimeter in diameter. "Notably, the PCNA S228I mutation impairs FEN1 and LIG1 interactions and results in clinical features, including short stature, hearing loss, premature aging, telangiectasia, neurodegeneration, and photosensitivity in humans." (PMID 37205694, 2023).
Tongue tumors (2 papers, 2017 to 2019). "The PCNA‐positive cells in tongue tumors of DOX+ iDek mice were significantly higher than those of DOX+ iDek mice." (PMID 28834425, 2017). "Tongue tumors overexpressing DEK showed increased proliferating cell nuclear antigen and elongator complex protein 3 expression." (PMID 28834425, 2017). "IHC staining of the tongue tissues indicate that treatment of mice with LOXL2 inhibitor PXS-S1C decreased levels of PCNA and LOXL2 in LY2 tongue tumors." (PMID 31086173, 2019). "Furthermore, to clarify whether exogenous DEK‐FLAG protein induced PCNA overexpression in cancer cells, we performed double immunofluorescent staining for the FLAG tag and PCNA in tongue tumors of DOX+ iDek mice." (PMID 28834425, 2017).
type 2 diabetes (2 papers, 2011 to 2019). "We are investigating the protein levels of PCNA and p‐NPM in the PBMC samples from healthy subjects and those with type 2 diabetes, to obtain evidence that can link PCNA and NPM to centrosome amplification in type 2 diabetes." (PMID 30478982, 2019).
ulcerative colitis (2 papers, 2020 to 2023). An inflammatory bowel disease involving the mucosal surface of the large intestine and rectum. "Secondly, observation of relevant specific criteria of ulcerative colitis in our study involved evaluation of DAI, hematology parameters and HAI, supported by morphometric parameters, cell proliferation (PCNA) marker, Bcl-xL marker, and viability of microorganisms." (PMID 33271873, 2020). "Markers of cell proliferation PCNA (proliferating cell nuclear antigen) and cell apoptosis Bcl-xL and inflammatory markers iNOS (nitric oxide synthase) and COX2 (cyclooxygenase) were monitored by immunohistochemical analysis in the tissue of colon with chemically induced ulcerative colitis." (PMID 38255150, 2023).
acute liver failure (1 paper, 2023). Rapid deterioration of liver function causing encephalopathy and coagulopathy. "In the second model in which C57/B6 mice were injected with a single dose of acetaminophen (APAP) to induce acute liver failure, similar observations were made that Trib1 expression was down-regulated at 1d and 2d in the liver after APAP injection, which mirrored PCNA/cyclin D1/CDK4 up-regulation." (PMID 37355685, 2023).